IL6 (interleukin 6)
Diseases named in the same sentence as IL6 in open-access papers (continued):
Sharing a sentence is not in itself a finding about the gene and the disease.
infection (continued). "As IL6 levels are low for S.Tm infected mice, we also determined plasma Lipocalin-2 (LCN2), as an acute phase protein produced upon infection with Gram-negative bacteria." (PMID 34368018, 2021). "At early time points, Fpr2-/- mice showed a significant decrease in CXCL1, CXCL2, IL-1β, CCL2, GM-CSF, IL-6, and CCL3 levels at 1 hour and 3 hours after infection, and an increase in IL-22 and IL-23, but there is no change in TNF-α, as compared with WT mice." (PMID 34899755, 2021). "With the increased infection time, IL-1β and TNF levels did not consistently increase at 6 h postinfection compared to 3 h, whereas IL-6 and IL-10 did." (PMID 33664232, 2021). "In contrast, KO of TLR9 did not change the production of either IL-6 or TNFα, indicating that, in human macrophages, TLR9 is not a relevant or important receptor during the early stages of intracellular infection." (PMID 34280250, 2021). "In the absence of maltol, infection (NC group) with E. maxima increased (P < 0.05) the gene expression of TNFSF15 (3.4 × 10−3-2.3 × 10−2), IL-1β (1.9 × 10−3-4.9 × 10−3), and IL-6 (3.0 × 10−3-9.9 × 10−3) in the distal jejunum compared to that of the CON group." (PMID 34095279, 2021). "All the subjects originated from the Sundanese ethnic group, with normal liver function and no signs of infection or inflammation, and were characterized by normal CRP and IL-6 serum levels." (PMID 33954177, 2021). "We also observed that the inflammatory biomarkers CRP, IL6 and TNF-α were higher among patients who developed AKI compared to those who did not, which highlights the role of severe infection in the pathogenesis of AKI." (PMID 34577543, 2021). "Consistently, mRNA expression of IL6, IL8, COX2, and mPGES1 was significantly upregulated in PHGFs, but not in TIGFs following infection." (PMID 34031466, 2021). "Interleukin-6 (IL-6) and tumor necrosis factor–α (TNF-α) were similarly induced during active infection, regardless of ICI treatment." (PMID 34407944, 2021). "Specifically, in Caco-2 monolayers exposed to 500 ng/mL of 5-HT, expression and protein level of TNF-α, IL-6 and IL-8 were about 3 folds higher in MAP-infected monolayers compared to control cells without infection or 5-HT treatment." (PMID 34799637, 2021). "We measured the level of inflammatory cytokines, such as TNF-α and IL-6, in control and ELMO1 shRNA J774 cells after infection with WT Salmonella, with the sifA mutant, or with nonpathogenic bacteria, such as E. coli Nissle-probiotic strain and E. coli DH5α." (PMID 34719317, 2021). "Untreated animals showed elevated levels of IL-6 and IL-10 but not IL-1β and TNF-α, in their lungs 4 days after the infection." (PMID 34648602, 2021). "Significantly higher levels of IL-17, IL-1β, IL-6 and TNF-α were detected in BAL and lung tissue lysates from infected CS-exposed mice, compared to non-infected animals at 24h after infection." (PMID 33784296, 2021). "In the DIO mouse, infection with IAV led very early to a significant elevation of systemic pro-inflammatory cytokines, like IL-1β, TNF-α, IFN-γ, and IL-6, in obese mice compared to non-obese mice." (PMID 33810619, 2021). "IFN-β was secreted at low levels that did not vary significantly during infection, whereas IFN-α and IL-1α/β were produced in limited amounts and with kinetics similar to those of IL-6 and IP-10." (PMID 34607464, 2021). "Although TNF-α and IL-6 are both produced in the hyper-inflammatory condition of LgyLRV1+ infection, their regulation is different as PP2 can block secretion of TNF-α without affecting IL-6 levels." (PMID 33765083, 2021). "Infection induces cell-intrinsic expression of type I and type III interferons (IFNs) and interleukin (IL)-6 but not IL-1." (PMID 33730024, 2021). "After infection with a non-lethal dose of HSV1, we monitored serum IL-6 in wild-type and N4bp1−/− mice." (PMID 33654074, 2021).
infection (continued). "Clearly, on diagnosis of the infection patients with CVF presented higher levels of PCT, IL-6, pro-adrenomedullin and suPAR, regardless of the duration; however, at day 3 after diagnosis, high biomarker levels were found only in patients with persistent CVF." (PMID 34209181, 2021). "Since AdV 7 at 1 MOI induced significantly higher IL-6 expression comparing to cells without infection, we chose 1 MOI AdV 7 for infection for the downstream experiments." (PMID 33072092, 2020). "Consistent with previous findings, LCMV-infected WT mice showed a significant increase of CCL2 on day 3 postinfection and IL-5 on day 7 postinfection, only, while TNF, IL-1β, IL-6, IFN-γ, CCL1 and CCL22 levels did not change following infection." (PMID 32310998, 2020). "Infection with B. abortus at MOI 100 and 1,000 induced IL-6 but not IL-1β nor TNF-α (not shown) secretion by both pre-adipocytes and adipocytes." (PMID 33071987, 2020). "IL-6 as a biomarker for infection in EOS is not as well-known as CRP and the cut-off value for infection is uncertain." (PMID 33218324, 2020). "Here, serum IL-6 and TNF levels in mice were not affected, however IL-10 was attenuated at 14 d post-infection." (PMID 32482929, 2020). "On the other hand, Nc-Spain7 infection did not upregulate TGF-β1, IL-6 and IL-17A expression in bovine placentas at any time assayed." (PMID 32552750, 2020). "Accordingly, Siglece−/− mice produced more IL-6 and TNF-α than wild-type littermates after infection with E. coli 25922 or DH5α but not with S. aureus or L. monocytogenes." (PMID 32889432, 2020). "Increased levels of IL-1β, IL-6, and TNFα were detected in sera of PLGA-PEG-treated mice both in the presence and absence of C. albicans-infection (respectively)." (PMID 33091017, 2020). "In the V+H1N2var group, the mean concentrations in haptoglobin, IL-6, and TNF-α have not been changed as compared to the Control group either, but individual responses to the infection appeared to be heterogeneous, as shown by the large standard deviations." (PMID 33053905, 2020). "Hepatic leukocytes from TgAlbCre-IL10-/- mice produced the highest levels of NO and IFN-γ, while the levels of IL-6, TNF and MIF were increased upon infection but not different between the groups." (PMID 32012211, 2020). "However, during EAEC infection, proinflammatory cytokines could enhance mucus secretion through enterocytes, since among the E. coli pathotypes, EAEC is the best inducer of TNF-α secretion in epithelial cells and induces the secretion of TNF-α, IL-6, or IL-1β by macrophages." (PMID 33281812, 2020). "Interestingly, the discharged patients with recurrence of positive SARS-CoV-2 RNA had an elevated serum IL-6 level and lymphocyte count compared to those with no recurrence, indicating that the immune system may still be actively involved in clearing the infection." (PMID 32909961, 2020). "TNF-α, IL-6, CXCL1, CCL2, and CCL7 levels significantly increased in the sera of klotho WT and KO mice at 1 day post-infection, while the level of IL-12 was not." (PMID 33329595, 2020). "In the absence of infection, the treatment with all four oleoresins and SDZ + PYR did not alter IL-6 and MIF production in comparison to uninfected and untreated villous explants (control group)." (PMID 32938966, 2020). "A study conducted by Reveille revealed that in AS patients in the inflammatory stage, inflammatory markers such as C-reactive protein (CRP), IL-6, and erythrocyte sedimentation rate (ESR) were often higher than normal values, while infection did not exist." (PMID 31395063, 2019). "Upon clearance, the release of pro-inflammatory cytokines, such as IL-6, IL-8, and TNF-α, will decrease, reducing Mφ trafficking to the site of infection without altering PMN migration." (PMID 31412039, 2019). "We also found that protein levels of IL-6, IL-12p40, IL-12p70, CCL2, CCL3 and CCL4 were not suppressed in response to rosiglitazone treatment during super-infection." (PMID 31159430, 2019).
infection (continued). "The optimal cutoff levels of PCT, IL-6, sCD163, MNV, MMS, and MLV were calculated between the infection group and the noninfected control group by drawing the receiver operating characteristic curves." (PMID 31915467, 2019). "The induction of cytokines (IL6 and TNFα), chemokines (CCL2 and CXCL10), and IFN-I genes in primary C57BL/6 astrocytes following a TMEV-BeAn infection can be mediated by TLR3 but not TLR7 or other MyD88-mediated pathways." (PMID 30669615, 2019). "Anti-Brucella antibodies abrogated the production of IL-6, IL-10, and IL-12 but did not affect the levels of IFN-γ at later stages of infection in PMNd-Br mice." (PMID 30804100, 2019). "In contrast, no significant induction of expression of IL6, LITAF, and cytokine IL10 was detected after infection with the different Salmonella strains." (PMID 31998655, 2019). "In contrast, we observed significantly enhanced expression of Cxcl1 (KC), Il6, and Il17, but not of Cxcl2 (MIP-2), Ifng, or Il10, in the huLangerin group as opposed to WT controls after infection with the S. aureus ΔtarM mutant." (PMID 31088921, 2019). "The pro-inflammatory cytokines, including IL-1, IL-6, IL-8, and TNF-α, have been demonstrated to play an important role in delivery, which is independent of the presence of infection." (PMID 31113485, 2019). "Immunization and/or infection did not alter cytokines IL-2, IL-4, IL-10, IL-17, IFN-γ, and TNF-α levels; however, IL-6 significantly (p < 0.05) increased, as compared with untreated control." (PMID 31065302, 2019). "Tissue models with T84 and HEC-1-B cells produced less IL-6 than those with SV-HUC-1 cells, and we observed no greater differences between the bacterial strains and derivatives used for infection, except for N927 in the Transwell® model." (PMID 31417529, 2019). "In the absence of infection, endogenous IL-6 protein was barely detected in the cerebral cortex of WT or TLR7-/- mice, whereas upon EV71 infection IL-6 levels were significantly elevated in the cerebral cortex of WT mice relative to TLR7-/- mice." (PMID 31730654, 2019). "In 2006, another group demonstrated that prolonged stimulation with the CAP67 mutant increases expression of IL-6 in PBMC and results in resolution of infection, whereas that does not occur encapsulated fungus." (PMID 31275938, 2019). "G-CSF, IL-6, KC, MCP-1 and MIG showed significant effects of infection status (p < 0.0001) but not genotype." (PMID 31013822, 2019). "The term placenta exhibited a robust innate immune response to infection by LCMV, marked by induction of ifn-α, il-6, and tnf-α gene expression which was not seen in the first-trimester explants." (PMID 30882005, 2019). "3D PHH cultures themselves do not produce any IL-6 and TNF-α in response to infection with HBV since these cytokines are KC specific." (PMID 29445209, 2018). "For LEC+ stimulation, however, addition of anti-IL-6 antibody did not completely reduce the infection level to that of unstimulated resting cells, suggesting that for LEC+ cells, factors other than IL-6 were also involved in stimulation of resting T cells." (PMID 30285810, 2018). "Among the cytokines expressed by BMDMs infected with O. tsutsugamushi, the levels of IL-6 and IL-10 were significantly reduced in cells lacking IFNAR at 36 h after infection when compared to those of wild type macrophages." (PMID 30233599, 2018). "Infection of DCs with Rift Valley Fever virus (RVFV) induces the expression of TNF-α, IL-6, and IL-10 but not IL-8, IL-19, or IL-1β17." (PMID 30401896, 2018). "After 1 day, T cells stimulated by LEC, with or without anti-IL-6 antibody, were infected, and GFP levels were measured on day 6 or 7 post-infection." (PMID 30285810, 2018). "To quantify changes in protein expression of LNCaP-based cells upon re-expression of JAK1, cytokine treatment and/or infection, we applied SILAC to cells stimulated with IFNα or IL-6 and infected or not with EHDV-TAU." (PMID 29441069, 2018).
infection (continued). "Infection of DCs by dengue virus, though, leads to cell maturation and production of TNF-α and interferon (IFN)-α, but not IL-6 and IL-1218." (PMID 30401896, 2018). "Addition of isotype control antibody, anti-IL-1β, IL-6, or IL-10 antibodies did not significantly affect the generation of T cells expressing IFN-γ or TNF-α during in vitro infection and T cell priming." (PMID 30233599, 2018). "Live calves (CC), had higher plasma concentrations of SAA and IL-6 than dead calves with (PM INF+, SAA P < 0.05; IL-6 P < 0.01) or without in utero infection (PM INF-, SAA and IL-6 P < 0.01)." (PMID 30382887, 2018). "Together, these results suggest that Tc infection induces a significant increase in PPAR-α expression and TNF-α and IL-6 production in Mφs; however, PPAR-α is not the prime regulator of the pro-inflammatory cytokine response in infected Mφs." (PMID 29503646, 2018). "By contrast, production of TNF-α, IL-6, and IL-10 did not change in G2A KO BMDMs with or without LPC treatment during H37Ra infection." (PMID 29755479, 2018). "During early infections [2 hours post infection (hpi) and 24 hpi], upregulation of IFN-β, TNF-α, IL1β, and IL-6 cytokines, with little to no IL-10, was observed in DENV-infected primary human macrophages, despite ADE." (PMID 29740424, 2018). "IL-6, CXCL10 and TNF-α concentrations were undetectable in many of the animals regardless of infection status." (PMID 29391069, 2018). "This is why under IL-6 inhibition CRP levels are often not measurable and cannot be used to monitor disease activity or to detect infections." (PMID 29622022, 2018). "To test if SOCS3 protein is induced by IL-6 (with or without infection), we pretreated (or not) LNCaP-JAK1 cells with IL-6 (5 ng/mL, 12 h) and subsequently infected or not these cells with EHDV-TAU (moi = 0.5, 48 h)." (PMID 29441069, 2018). "In contrast to live infection, H1N1 HA actually inhibited pneumococcus induced IL-6 (n = 3), whereas H3N2 HA did not." (PMID 30192848, 2018). "Our data suggested that NOD2 activity began to increase in brain tissue 12 h after infection, while those of IL-1β, TNF-α, and IL-6 showed no obvious changes at 12 h." (PMID 30186539, 2018). "Human metapneumovirus (hMPV) infection prevents the nuclear translocation of STAT3 in a cytokine-specific manner, as this was only observed following stimulation with IL-6 and not in case of interleukin 22 (IL-22)." (PMID 29543893, 2018). "However, in the presence of high tissue concentrations of IL-6 these cells might lose their suppressive capacity temporarily to help fight infection, an effect that would not be advantageous in a site of chronic inflammation in which a pathogen was not present." (PMID 28284938, 2017). "ELISA analyses revealed that CSF3, IL-1β, and IL-6 proteins were induced by EV71 or R848 (a TLR7 agonist) as a stimulus control, but not by mock-infection or UV-inactivated EV71, in THP-1, macrophages, and human PBMCs." (PMID 28854257, 2017). "The purpose of this study was to investigate the diagnostic value of the preoperative laboratory protocol including IL-6, WBC, CRP, and ESR in bone nonunion patients with suspected infection." (PMID 29130050, 2017). "At 24 h post-infection, S. aureus infection without antimicrobial treatments showed a significant (P < 0.05) increase in TNF-α and IL-6 compared to snipped only glands with no S. aureus inoculation." (PMID 29255451, 2017). "In terms of cytokine expression, compound-6 treated mice had significantly higher expression of IL-6 (lung and brain), IL-4 (lung and brain), IFN-γ (lung and brain), TNF-α, IL-β1and IL-12 (lung) when compared to control group (without infection)." (PMID 29133871, 2017). "The network analysis revealed a strong correlation between IL-6 and MCP-1/CCL2, regardless of parasite load, suggesting that these mediators were induced by the infection itself." (PMID 28118834, 2017).
infection (continued). "In addition, previous studies have demonstrated that MSCs may participate in the mitigation of infection by secretion of soluble paracrine factors including interleukin (IL)-10, prostaglandin E2 (PGE2), tumor necrosis factor (TNF)-α-stimulated gene/protein 6, and IL-6." (PMID 28114965, 2017). "In Hsd11b1Del/Del mice, only IL-4 and TNF-α were significantly increased in response to the infection (respectively, p = 0.0061, 0.0061), and non-significant trends were noted for IFN-γ, IL-5 and IL-6 (respectively, p = 0.103, 0.109, 0.103)." (PMID 29062028, 2017). "IL-1β, IL-6, IL-8, and IL-12 mRNA expression were also increased in Ab4 infected EREC, whereas no modulation was described after PBMC infection." (PMID 28925977, 2017). "It was observed that rTgHSP70 immunization did not alter the production of IL-2, IL-4, IL-6, IL-10, IL-17a, IFN-γ, nor TNF, although infection with T. gondii promotes the production of inflammatory cytokines IL-6, IFN-γ, and TNF in all groups of mice." (PMID 28487847, 2017). "It is worth noting that the correlation between A-FABP4 plasma levels and plasma IL-6 and CRP persisted in patients without infections." (PMID 28500294, 2017). "We found that macrophages from gp91phox−/− and WT mice produced similar levels of IL-6, TNF-α, IL-17A and CXCL-1, MCP-1 and IL-10, regardless of infection with L. amazonensis." (PMID 27056545, 2016). "There were minimal levels of serum IL-6, CCL2, CXCL1, and TNF-α in mice without CVB3 infection, while those infected with CVB3 had significantly increased inflammatory cytokines and chemokines on day 5 post infection, which might be associated with exacerbation of pancreatic inflammation." (PMID 27195463, 2016). "Unlike H5N1, H1N1 induced significantly lower levels of IL-6, MCP-1 and TNF-α at 24 h post-infection; and MCP-1, TNF-α, IL-10, IFNL1 and IFN-β at 48 h post-infection when compared with H7N9-CK or H7N9-HU." (PMID 26975414, 2016). "We observed a progressive elevation of serum cytokine and chemokine levels including IL-6, IL-1β, IFN- α, IFN- γ, IL-17, and IL-1Ra beginning 24 h post-infection; only IL-12p40 was not elevated." (PMID 27855182, 2016). "This analysis revealed significantly higher levels of several cytokines in aged and young mice following infection (compared to PBS controls) at 24 h p.i., including IL-6 and MIP-1β, which were not significantly elevated in dam mice." (PMID 27936166, 2016). "Upon infection with S. aureus, WIM-6 mice with Nrf2 knockout showed much more intense IL6-luc luminescence on their back than the WIM-6 mice with normal Nrf2 expression showed." (PMID 27211851, 2016). "GSEA revealed that genes from the MyD88-mediated pathways (P = 0.019) and IL-6, IL-10 and G-CSF cytokine pathways (P = 0.033) are highly enriched during HN878 infection when compared to non-infected samples." (PMID 25790379, 2015). "Infection of H69 cells by RRV was noncytolytic and resulted in a time-dependent increase in the release of both infectious virions and cytokines IL-6 and IL-8 into the supernate." (PMID 26247025, 2015). "In the univariate analysis, levels of LBP, IL-10, IL-6 and CRP were compared between patients with and without infection." (PMID 25613713, 2015). "In the univariate analysis, levels of LBP, IL-10, IL-6 and CRP significantly differed between patients who developed an infection and those who did not." (PMID 25613713, 2015). "At an earlier time point (24 hours post infection) we found no significant change in B2-m, MMP3, or IL-6 levels." (PMID 25573478, 2015). "In EBOV infection, pro-inflammatory cytokine production is correlated with lethality, as TNF-α, IFN-γ, IL-1β, IL-6, IL-8, MCP1, MIP-1α, and MIP-1β levels are increased in fatal versus non-fatal infection." (PMID 26426036, 2015). "At 5 days post-infection, IFN-γ, IL-6, IL-12p40 and nitric oxide(NO) levels were not significantly different in the serum and the ascites fluidbetween the wild-type and CCR5−/− mice (data notshown)." (PMID 25558986, 2015).